CD44 (CD44 molecule (IN blood group))
Diseases named in the same sentence as CD44 in open-access papers (continued):
Sharing a sentence is not in itself a finding about the gene and the disease.
tumor (continued). "Similarly, CSC expressing high levels of CD44 were found to significantly elevate TNF-α secretion along with other inflammatory cytokines such as Interleukins (IL-1beta, IL-10, IL-12) and angiogenic factors (Angiopoietin-1 & 2, VEGF, and bFGF) owing to increased oral tumor stemness." (PMID 38170015, 2023). "Moreover, C44Mab-18 could stain tumor cells, but not stromal tissues, which could be stained by C44Mab-46, an anti-pan-CD44 mAb." (PMID 37504249, 2023). "In addition, the CD44+/CD24−/low phenotype may not necessarily correlate with clinical outcomes due to the tumor-type-dependent frequency of BCSC." (PMID 37445860, 2023). "However, whether the tumor-suppressor gene LOC339059 promotes the differentiation of cancer cells still requires more experiments to validate its effect on the molecular differentiation markers b-catenin, CD44, and Cyclin D1." (PMID 38001573, 2023). "We then discussed the effects of other cell types on epithelial cells in tumor tissue, and the results indicated that immune cells could regulate epithelial cells through specific ligand–receptor pairs, such as TNFSF14-TNFRSF14, MIF-(CD74+CD44), IFNG-(FINGR1+IFNGR2), CXCL12-ACKR3, and CXCL11-ACKR3." (PMID 36569924, 2022). "Since we have previously shown that CD44 mediates cell aggregation via intercellular interaction, we utilized multiple experimental approaches to test whether ICAM1 also forms homophilic dimers from neighboring cells, thereby resulting in tumor cell aggregation." (PMID 34381029, 2021). "Furthermore, integrated analysis of TAMs from GBM and spinal ependymoma revealed that the CD44+ TAMs from the two tumors were closely related to each other, but they did not overlap in the UMAP plot, indicating that they had their own characteristics in each tumor." (PMID 34824203, 2021). "Moreover, transcription factor hypoxia-inducible factor 1-alpha (HIF1α) and the biological interaction between HER2 and CD44 may lead to upregulation of C-X-C chemokine receptor type 4 (CXCR4), which promotes tumor progression and NCRT resistance in gastroesophageal cancer." (PMID 33151397, 2021). "Furthermore, the expression levels of CD44, CCND3, NCALD, MACF1 and KCTD15 were downregulated in the vast majority of LUAD histological subtypes compared with in normal samples, and they were differentially expressed according to tumor stage and nodal metastasis status." (PMID 33281971, 2021). "In addition to the recombinant Eno1 proteins, the partial silencing of CD44 in EO771 tumor cells reduced the inhibitory effect of recombinant Hsp90ab1 proteins on MTT-based viability, and partially suppressed the Hsp90ab1-driven downregulation of Lrp5, Runx2, and TGFβ in EO771 tumor cells." (PMID 34830748, 2021). "Additionally, in vitro experiments demonstrated that Hs578T cells lacking CD44 exhibited impaired wound closure and increased HA production, factors that may also contribute to the delay in tumor formation." (PMID 32455980, 2020). "Interestingly, the tumors generated from the tumorigenic CD44+/CD24neg/low/ESA+ cells also contained a diverse and mixed population of cells (tumorigenic and non-tumorigenic) that were present in the primary tumor, which is a characteristic that was indicative of the plasticity of the tumor." (PMID 32883003, 2020). "In addition, the levels of ERα and CD44 were lower in the IBC group than in the control group by immunohistochemical (IHC) staining and IPP software analysis, and a positive correlation was observed between ERα and CD44 in MCF‐7/R mouse xenograft tumours treated with IBC." (PMID 30179299, 2018). "Given to a tumor consists of heterogeneous cell populations, we could easily replace the binding domain of CXCR4-KLA with other ligands to target other CSCs that express different cell-surface biomarkers such as CD133, CD44, CD117, and MyD88 of OVC in the future." (PMID 28196146, 2017). "However, the roles of CD44 are lack of investigation in tumour stroma like fibroblasts." (PMID 28523716, 2017).
tumor (continued). "Finally, it should be noted that down-regulation of miR-34a by XRN1 might contribute to PCa progression independent of AR, since miR-34a can act as a tumor suppressor through directly inhibiting CD44 in tumorigenic and metastatic PCa stem cells." (PMID 25797256, 2015). "However, ANV cells were not able to generate CD44+CD24+ primary MMC tumor cells, in vitro." (PMID 24324806, 2013). "Interestingly, a group of CD44+ESA+ cells were also found to be significantly enriched in the invasion front of metastatic tumour, suggesting that these CSCs may be responsible for the growth of the tumour cells in the brain." (PMID 23495140, 2013). "Moreover, it has been shown in vivo that sulfated hyaluronan augmented tumor growth due to a blockade in complex formation between phosphoinositide 3-kinase (PI3K) and hyaluronan receptors and to a transcriptional downregulation of HA receptors, CD44, and RHAMM, along with PI3K inhibition." (PMID 24083250, 2013). "Furthermore, this tumor formation and heterogenic recapitulation could be replicated upon serial passaging in naïve NOD/SCID mice of the ALDHhi CD44+ CD24− cells isolated from tumors derived from the initial CSC injection, demonstrating the CSCs' differentiation and self-renewal potential." (PMID 22295241, 2012). "Additionally, the fact that CD44 and Tenascin C are expressed at much higher levels in the perivascular astrocytes when compared to peritumoral astrocytes suggests subtle differences between the two populations of non-neoplastic tumor astrocytes." (PMID 22393407, 2012). "Mack and colleagues questioned the use of CD44 as a specific CSC marker in HNSCC since CD44 was abundantly expressed in most tumor cells within HNSCC (60%-100%) and therefore could not be used to distinguish normal from benign or malignant epithelia of the head and neck." (PMID 21304586, 2011). "Furthermore, the tumours that arise in mice injected with purified CD44+CD24− LNCaP cells are phenotypically diverse, containing primarily CD44−CD24− and CD44−CD24+ cells and only a small percentage of CD44+CD24− cells, similar to tumours derived from injecting the total LNCaP cell line." (PMID 18268494, 2008). "Notably, the proportion of CD44+CD62L- EMT cells was markedly greater in CPIP@EV–CM + US treated group (11.1%) than PBS treated group (3.1%), indicating that CPIP@EV–CM + US could produce a strong immune memory effect and prevent tumor metastasis and recurrence in mice." (PMID 40854883, 2025). "Gene expression analysis in tumor tissues revealed that ACN, whether used alone or in combination with DOX, significantly downregulated several key genes associated with BC metastasis, such as HIF, Cd44, Rgcc32, CREB, PI3K/Akt-1, which were not effectively suppressed by DOX alone." (PMID 40806360, 2025). "While CD44, E-cadherin, CD166 and EpCAM were expressed in the medial membranes of tumor cells, they were not expressed in the tumor buddings in a recent study." (PMID 40564019, 2025). "Levels of miR-9-5p are elevated in CD44+ prostate cancer stem cells (PCSCs) and exhibit a negative correlation with the expression of NUMB, a tumor suppressor in PCSCs." (PMID 40710326, 2025). "Immunohistochemistry for CD44 and ALDH1 on patient tumour specimens did not demonstrate a relationship with smoking status, supported our in vitro findings." (PMID 40282522, 2025). "Immunohistochemistry staining for CD44, TGF-β, and VEGFA1 was performed in lung tissues of A549 tumor-bearing mice, which revealed that regardless of RT, JMJD6-knockdown tumors had decreased positivity of CD44, TGF-β1 and VEGFA1 compared with control tumor." (PMID 41320721, 2025). "We compared CD44 and ALDH1 expression in tumour biopsies from never-smokers (seven patients) and smokers (nine patients)." (PMID 40282522, 2025). "Looking into the TME, the OVA-specific CD44+ CXCR6+ CD8+ cells expressed higher levels of PD-1, suggesting a lower immune response; thus, in these mice, the immune system failed to prevent tumor growth." (PMID 38774646, 2024).
tumor (continued). "Next, CD44+ PD-1+ Tim3− stem-P14s were sorted from the TdLNs and transferred into B16F10GP tumor-bearing mice, followed by treatment with RT with or without anti-PD-L1 3 days later." (PMID 38496632, 2024). "For specific tumor types that do not seem to produce EpCAM + CD45- cells, the classification based on high CD44 and low CD24 expression (CD44 + /CD24 − /low) has been introduced." (PMID 38331871, 2024). "In addition, the frequency of effector memory T cell (TEM) (CD3+ CD8+ CD44+ CD62L−) in mU@OMVs treated mice increased by 29.93% compared with that of PBS control, demonstrating that mU@OMVs could induce potent long-term immune memory effects to prevent tumor recurrence." (PMID 36966130, 2023). "Conversely, upon evaluating OT1s infiltrating tumor, a heterogenous pattern of CD62L expression was observed, with no detectable expression of CD44." (PMID 38099496, 2023). "CD44 was highly expressed (roughly 85%) in our CMT samples, regardless of the tumor grading, as well as in the healthy mammary gland tissues." (PMID 36899736, 2023). "In FFPE-ESCC tumor samples, wherever there is a strong appearance of MMP9, the CD44 is diminished greatly or nonexistent while appearing highly expressed just nearby." (PMID 36671668, 2023). "The difference lies in the tumor stem cell marker genes, where CD133 was not highly expressed, but CD44 showed high transcription." (PMID 37880655, 2023). "On this basis, an in vitro study showed that PtNPs encapsulated in hyaluronic acid (HA-PtNPs) accumulate in tumor cells, overexpressing CD44 (MDA-MB-231 cells) when compared with nonfunctionalized PtNPs and in cells not expressing CD44 (NIH3T3 cells)." (PMID 37514119, 2023). "In other cases, the CD44+CD271+ staining patterns were less organized, irrespective of tumor differentiation." (PMID 35215208, 2022). "The expression of stem cell markers was also evaluated on primary tumor cells from 55 PDAC patients who underwent pancreatectomy with radical intent, revealing that CXCR4+/CD133+ and CD24+ cells, but not ESA+CD24+CD44+, are independent predictors of mortality." (PMID 36142575, 2022). "In an experiment which assessed stemness of tumor cells using in vitro clonal formation assay, a subtype of CD44v6+ epithelial membrane antigen-negative (EMA-) BCSCs were isolated by using CD44 splice isoform (CD44v6)." (PMID 35903544, 2022). "The CD44/CD24 ratio expressed on INJ, PUMP (ASA), and PUMP (OP) treated tumor tissues was not significantly different from GEM-treated tumor tissue." (PMID 35892853, 2022). "A bioinformatics analysis through TIMER online web tool with default settings showed significantly increased messenger (m)RNA levels of CCNB1/CDC42/MAPK7/CD44 in pan cancers, including GBM tumor tissues compared to normal tissues from TCGA)." (PMID 35008426, 2022). "CD24, CD44, laminin, CD49, CDX2, CK6 and DAXX had lower expression in the tumour relative to that in the non-tumour tissue." (PMID 36362433, 2022). "Furthermore, the SPP1/CD44-mediated crosstalk between SPP1+ macrophages and cancer cells in the SPP1+ macrophage-enriched region formed a specific niche to accelerate the malignant progression of GC, which means that the architecture of intratumor heterogeneity may evolve with tumor progression." (PMID 36612160, 2022). "In G2, CD56, CgA, NSE, vimentin and Ki-67 were higher in tumour tissue compared to those in non-tumour, and levels of CD44, CD45, CK7, DAXX, synaptophysin and PDX1 were lower in tumour tissue relative to those in non-tumour tissue." (PMID 36362433, 2022).
tumor (continued). "The secretome formulation significantly decreased CD44+/CD24−, MDR1+ and PDL1+ populations in triple-negative breast cancer cells and declined the in vivo tumor growth." (PMID 36550571, 2022). "In the present study, CD44 and RHAMM expression levels were evaluated in pretherapeutic tumor tissues from FL patients, both with and without subsequent HT." (PMID 35267625, 2022). "The levels of PD1 on CD8+ T cells were elevated in mice bearing MC38 VPS OE tumors, while CD44, CD107, CD62L, and CCR7 expression were not significantly different in either spleens or allografted tumor tissues." (PMID 36458816, 2022). "Again, transfection with miR-637 inhibitor failed to increase the number of tumor spheres and up-regulate the expression of stemness-related genes (SOX4, SOX9, Nanog, CD44 and ABCG2) after stable knockdown of WASH in KYSE70 cells." (PMID 36329557, 2022). "A significant correlation between tumor markers ALDH1-A1, -A2, and -A3, CD24, CD44 on one hand, and CD276, on the other hand, was not computed." (PMID 35563359, 2022). "As expected, treatment with TS120-A or TS120-D peptides did not alter the levels of TSPYL5, CD44, or PTEN in tumor cells from the in vivo models." (PMID 34163000, 2021). "Orthotopic tumour models were developed from CD44+, CD44+ α2β1+, ALDH+ CD44+ α2β1+ and ALDH+ CD44+ CXCR4+ CD24+ cells with or without HOXB9 knockdown." (PMID 34247196, 2021). "Though the signaling cascades downstream of CD44 is not well-characterized, it is known that CD44 activates different signaling pathways like Rho GTPases, Ras-MAPK, and PI3K/AKT pathways to regulate different tumor properties." (PMID 34150761, 2021). "This subpopulation of BC cells is known to be CD44 positive (CD44+/+) with negligible or no CD24 (CD24low/−) and are responsible for the acquisition of chemoresistance properties and tumor recurrence." (PMID 33745223, 2021). "In preclinical studies in mice, CD44-targeted NIR-PIT, combined with an immune checkpoint inhibitor, achieved complete tumour killing including metastatic lesions that were not exposed to NIR light." (PMID 34332294, 2021). "This indicates that the role of CLDN1 in tumor metastasis and in the enhanced presence of CIC markers CD44 and CD133 is not due to EMT pathway induction." (PMID 33828978, 2021). "It has been reported that CD44−/CD24+ and ALDH1+ tumor cells represent two distinct tumor cell populations not only localized in different regions of the primary tumor tissue but also expressing distinct EMT and MET gene profiles." (PMID 32667137, 2020). "Early studies showed that CD44+/CD24− cells were enriched in the bulk cell population and mammospheres were elevated following neoadjuvant chemotherapy in isolated tumor cells, regardless of receptor subtype." (PMID 33003540, 2020). "Within EDW01, but not ED03, there were regions of tumour cells that appeared to lack both CD24 and CD44; however, these regions in EDW01 that are negative for CD44/CD24 do not increase over passage number." (PMID 33276802, 2020). "CSCs can be identified from tumor-differentiated cells by MHC class I negative or decreased levels, CD54, PD-L1, as well as an increase in CD44 expression." (PMID 32391048, 2020). "At the time point of 2 days after the seeding, the CD44+/EPCAM+ cells had formed non-adherent spheres in culture, and more than 50% of these tumor spheres were either small or medium in size, with a total area below 16.000 μm2." (PMID 32391123, 2020). "Tumor growth was observed after implantation of CD105+, CD44+, CD44−, CD44−/CD105+ and CD44−/CD105− but not CD105− or CD44+/CD105+." (PMID 32214151, 2020). "Further analysis of tumor tissues, confirmed the in vitro results that when compared to the vehicle-treated group, SF + MU treatment downregulated phospho-MET, and CD44 levels in EV tumors, but not in A9 tumors." (PMID 32427869, 2020). "However, the results may not be stable between CD44 expression and tumor grade and T stage." (PMID 32434417, 2020).
tumor (continued). "Overexpression of IL-1β in mammary 4T1 tumor cells can modify MDSC phenotype (more CD8, CD80, CD83, and CD14 expression and lower CD44 and B220) in vivo, while it does not change their capacity to dampen CD4 and CD8 T-cells’ activation/proliferation." (PMID 32635472, 2020). "Remarkably, SW620 cells, which are derived from a metastasis of the same tumor from which the SW480 cells were derived, only express CD133 and CD44v6, but do not longer express CD44." (PMID 31139149, 2019). "First, exposure of purified, non-CSC to IFN-β prevents OSM-mediated CD44 and SNAIL expression and represses tumor sphere formation and migratory capacity." (PMID 31036052, 2019). "BI 853520 treatment, however, did not alter tumor stem cell marker (SOX2, ALDH1, NANOG, c-myc, CD44, Oct4) expressions of human tumor spheroids formed by different MPM cell lines." (PMID 30539198, 2019). "In particular, a subset of β-catenin-positive cells from HNSCC, expressing the tumor stem cell marker CD44, were also shown to co-express CD24 and CD29 and to promote non-adherent tumor sphere growth and seed tumors at low numbers in mice." (PMID 30029671, 2018). "Though by no means fully clarified, CD44/CD44v6 unequivocally contributes to niche embedding, apoptosis resistance, EMT, and tumor progression." (PMID 30211160, 2018). "Established GICs clearly display mesenchymal traits, greater clonogenic capacity, have greater self-renewal and tumorigenic capability, and express more L1CAM, CD44, CD133 and ITGA6 compared to the non-GIC tumor bulk cells." (PMID 29088733, 2017). "To confirm the lack of a tight link between CD133 expression and tumor formation, we stringently sorted untreated or serum‐treated PDAC cells according to their CD133 (P2, P3) or combined CD133/CD44 (P1) expression." (PMID 28526679, 2017). "As we observed minimal to no expression of CD44 in our stem cell lines, we wanted to examine if GBM tumor cells mediate stem cell migration." (PMID 28279210, 2017). "Like CD44+CD24+ESA+ cells, 500 CD133+ PC cells generated visible tumors that histologically indistinguishable from the primary tumor." (PMID 28245823, 2017). "Xenografted cells replicated the phenotype of the original tumour, displaying high expression of nestin, nf-200 and CD133, and no expression of CD15, CD44, GFAP." (PMID 28417956, 2017). "To test this, we monitored the expression of the differentiation markers, CD44 and CD62L, in SIINFEKL-activated CD8+ T cells from OT-1 mice co-cultured with tumor-MDSC or non-suppressive immature myeloid cells (iMC)." (PMID 27007050, 2016). "CD44 has been identified as a potential CSC marker in CRC and has also been shown to be a more selective colon CSC marker than CD133 since decreased expression of CD44, but not CD133, has been shown to reduce both clonal formation and tumor formation." (PMID 27411517, 2016). "Despite the fact that CD44 and CD24 are expressed in most tumours and are commonly used to identify CSCs, they are not specific to all cancers, and in addition, they can be also found in ESCs." (PMID 27766946, 2016). "The abstracts of the remaining 95 articles were further assessed by 2 observers independently, among which 59 articles were excluded due to non-CD44/CD133-related studies, nonimmunohistochemical research, not tested in tumor tissues." (PMID 27759647, 2016). "Injection of 1000 HNSCC CSCs that were ALDH+CD44+ let to tumor development in 13 of 15 mice, while injection of 10,000 non-CSCs which were ALDH−CD44− only led to tumor development in 2 of 15 mice." (PMID 26907349, 2016). "The EpCAM+ CD44+ CD47+ MET+ phenotype is common and was found in the circulation of all patients at varying frequency, including the vast majority whose circulating tumor cells were not tumorigenic." (PMID 28721373, 2016).